MIR34A (microRNA 34a)
Diseases named in the same sentence as MIR34A in open-access papers (continued):
Sharing a sentence is not in itself a finding about the gene and the disease.
tumor (continued). "Furthermore, we identified multiple, additional hallmarks of CACs harboring Mir34a-deficient myeloid cells, such as increased expression of Mmp9 in neutrophils and elevated expression of Zeb2 in an inflammatory subtype of CAC tumor cells." (PMID 39425000, 2025). "Their research indicates that Mir34a suppresses PDAC growth through controlling the immunological environment of the tumor, suggesting that reactivating Mir34a could be a helpful therapeutic strategy for slowing the disease’s progression." (PMID 38725047, 2024). "However, when Mir34a and Csf1r were inactivated concomitantly in IECs, the effects of single gene inactivations on tumor size and its distribution were largely neutralized." (PMID 36147476, 2022). "Therefore, Mir34a functions as a non-cell autonomous suppressor of CAC formation in tumor-associated myeloid cells." (PMID 39425000, 2025). "Therefore, the up-regulation of Csf1r as a consequence of Mir34a inactivation in intestinal adenomas is an important mediator of tumor/stroma interactions, which may promote tumor initiation and progression." (PMID 36147476, 2022). "In addition, our expression analyses showed that, among potential Mir34a targets, genes associated with the induction of STAT3, JUN and SRF expression signatures are presumably involved in the opposing regulation of intestinal homeostasis and tumor formation by Mir34a and Csf1r signaling." (PMID 36147476, 2022). "Several studies confirmed that Mir34a is downregulated in PDAC and many other cancers (reviewed in10,24,25) and that it blocks tumour growth by inhibiting genes involved in various oncogenic signalling pathways." (PMID 32541781, 2020). "However, the exact mechanism by which Mir34a exerts its tumour suppressor role in PDAC is not clear yet." (PMID 32541781, 2020).
cancer (9 papers, 2014 to 2026). A tumor composed of atypical neoplastic, often pleomorphic cells that invade other tissues. "Taken together, myeloid Mir34a-deficient CACs show a prominent increase of cancer cells with enhanced inflammatory signaling, which display a partially mesenchymal signature and may therefore represent cancer cells with enhanced migratory and invasive capacities." (PMID 39425000, 2025). "The present results revealed that MIR34A rs2666433 AA and AG genotype carriers were 5.7 and 2.8 more likely to develop cancer than GG carriers." (PMID 33037254, 2020). "Mir34a is epigenetically silenced in numerous cancers, including PDAC, where Mir34a down-regulation has been associated with poor patient prognosis." (PMID 32541781, 2020). "MIR34A expression in the CRC specimens was significantly upregulated (median = 21.50, IQR: 7.0–209.2; P = 0.001) relative to the non-cancer tissues." (PMID 33037254, 2020).
cardiovascular diseases (1 paper, 2023). "Western blot analysis confirmed that the level of endogenous SIRT1 protein was severely reduced by overexpression of MIR34A, while the level of exogenous SIRT1 protein was not affected, which delayed the aging process in cardiovascular diseases." (PMID 37805704, 2023).
CNS tumors (1 paper, 2021). "Other miRNAs were also previously reported to regulate epithelial-to-mesenchymal transition (EMT) and participate in CNS tumors, such as MIR34A." (PMID 34204289, 2021).
MIR34A also shares sentences with these, for which no sentence is quoted: colitis (2 papers); lung carcinoma (2); myocardial infarction (2); bladder cancer (1); dysplasia (1); endometrial cancer (1); hematological cancers (1); idiopathic pulmonary fibrosis (1); neurodegenerative disease (1); neurological disorders (1); renal carcinoma (1); tuberous sclerosis complex (1); Type 2 diabetes (1).